DUS2 (dihydrouridine synthase 2)
Description:
Catalyzes the NADPH-dependent synthesis of dihydrouridine, a modified base found in the D-loop of most tRNAs. Specifically modifies U20 in cytoplasmic tRNAs. Activity depends on the presence of guanosine at position 19 in the tRNA substrate. Negatively regulates the activation of EIF2AK2/PKR.
Synonyms: URLC8; DUS2L; FLJ20399; SMM1
Tractability: Small molecule: a structure with a bound ligand is known. PROTAC: ubiquitination databases record sites on it; its protein half-life has been measured; a small molecule that binds it is known.
Target class: Enzyme; Oxidoreductase
Gene: Protein-coding gene on chromosome 16 (67,987,746 to 68,079,344, forward strand). Ensembl gene ENSG00000167264.
Subcellular location: Cytoplasm; Endoplasmic reticulum
Subcellular location (Human Protein Atlas): Cytosol
Pathways (Reactome):
Immune System: PKR-mediated signaling
Metabolism of RNA: tRNA modification in the nucleus and cytosol
Gene Ontology:
Molecular function: double-stranded RNA binding; FMN binding; NADPH binding; protein binding; protein kinase inhibitor activity; tRNA dihydrouridine synthase activity; tRNA-dihydrouridine20 synthase activity; flavin adenine dinucleotide binding; tRNA binding
Biological process: antiviral innate immune response; tRNA dihydrouridine synthesis; tRNA processing
Cellular component: cytoplasm; cytosol; endoplasmic reticulum; mitochondrion
Genetic constraint (gnomAD): Loss-of-function variants: 49 observed, 71.05 expected, observed/expected ratio (o/e) 0.69, 90% interval 0.55 to 0.88. The upper end of that interval is the gene's LOEUF score, 0.88, which puts it in group 3 of 6, group 1 being the genes least tolerant of losing a copy. Missense variants: 535 observed, 627.81 expected, observed/expected ratio (o/e) 0.85, 90% interval 0.79 to 0.92. Synonymous variants: 199 observed, 231.64 expected, observed/expected ratio (o/e) 0.86, 90% interval 0.76 to 0.97.
Homologues: Orthologues: chimpanzee DUS2 (99% identical), macaque DUS2 (98% identical), rabbit DUS2 (92% identical), pig DUS2 (92% identical), dog DUS2 (91% identical), guinea pig DUS2 (91% identical), mouse Dus2 (90% identical), rat Dus2 (89% identical), zebrafish dus2 (61% identical), tropical clawed frog dus2 (60% identical), Drosophila melanogaster Dus2 (45% identical), Caenorhabditis elegans dus-2 (37% identical). Paralogues in human: DUS1L (21% identical), DUS3L (20% identical), DUS4L (19% identical).
Diseases named in the same sentence as DUS2 in open-access papers:
DUS2 is named in the same sentence as 11 diseases in open-access papers, as found by Europe PMC text mining. Sharing a sentence is not in itself a finding about the gene and the disease. The quoted sentences say what the papers report.
lung carcinoma (4 papers, 2011 to 2018). "Human Dus2 (HsDus2) expression is upregulated in lung cancers, offering a growth advantage throughout its ability to interact with components of the translation apparatus and inhibit apoptosis." (PMID 26429968, 2015). "Notably, DUS2 is upregulated in many lung cancers, and while a corresponding increase in dihydrouridine in the cytoplasmic tRNAPhe has been observed, it is possible that changes in DUS2 levels similarly affect mt-tRNA modification and that this may also contribute to carcinogenesis." (PMID 28752201, 2018).
Hypertension (2 papers, 2017). The presence of chronic increased pressure in the systemic arterial system. "Nine SNPs were related (P < 0.01 in any one genetic model) to hypertension, and five of these SNPs (rs150854849 of DCLRE1C, rs202069030 of DUS2, rs139012426 of LOC100505549, rs12229654 at 12q24.1, rs76974938 of C21orf59) were significantly (P < 1.25 × 10−4) associated with this condition." (PMID 28562329, 2017).
Alzheimer disease (1 paper, 2022). A progressive, neurodegenerative disease characterized by loss of function and death of nerve cells in several areas of the brain leading to loss of cognitive function such as memory and language. "Dus2 is the eukaryotic enzyme responsible for the synthesis of D20 in tRNAs and is involved in some human cancers and in the detoxification of β-amyloid peptides in Alzheimer’s disease." (PMID 36551188, 2022).
colorectal cancer (1 paper, 2022). A primary or metastatic malignant neoplasm that affects the colon or rectum. "At the molecular level, the human DUS2 protein (hDUS2) was shown to act as an inhibitory factor of the interferon-induced protein kinase PKR – whose kinase activity is enhanced in melanomas and colorectal cancers." (PMID 35638108, 2022).
cancer (4 papers, 2012 to 2024). A tumor composed of atypical neoplastic, often pleomorphic cells that invade other tissues. "Increased expression of human dihydrouridine synthase 2 (hDus2) has been linked to pulmonary carcinogenesis, while its knockdown decreased cancer cell line viability, suggesting that it may serve as a valuable target for therapeutic intervention." (PMID 26143927, 2015).
DUS2 also shares sentences with these, for which no sentence is quoted: non-small cell lung carcinoma (2 papers); chronic kidney disease (1); diabetes (1); melanoma (1); schizophrenia (1); tumor (1).